NLRP3 (NLR family pyrin domain containing 3)
Diseases named in the same sentence as NLRP3 in open-access papers (continued):
Sharing a sentence is not in itself a finding about the gene and the disease.
kidney damage (continued). "Notably, NET-derived DAMPs, including cf-DNA, perpetuate renal inflammation by activating the TLR4/NLRP3 inflammasome axis, which triggers caspase-1-dependent cytokine maturation and establishes a self-amplifying “NETs–inflammasome–tissue injury” loop, a hallmark of progressive kidney damage." (PMID 41244813, 2025). "The close interrelationship between inflammation and CKD is also well established, with numerous studies highlighting the role of various inflammatory markers and the NLRP3 inflammasome in the progression of kidney damage." (PMID 40547366, 2025). "In CP-AKI, ginsenoside Rg3 effectively prevents cisplatin-induced kidney damage by activating the autophagy-mediated inhibition of the NLRP3 pathway, and this process can be blocked by autophagy inhibitor 3-methyladenine." (PMID 37077810, 2023). "Increased NLRP3 expression has been observed in patients with CKD, and inhibition of the NLRP3 inflammasome has been shown to ameliorate kidney damage in animal models of CKD." (PMID 37371054, 2023). "Since the expression of NLRP3, ASC, and caspase-1 was decreased, it is probable that kaempferol can alleviate kidney damage in DKD rats by inhibiting the NLRP3 inflammasome." (PMID 37215100, 2023). "Inhibition of NF-κB and NLRP3 by Bay11-7082 prevented their formation and activation, respectively, resulting in an improvement in established kidney damage in LN." (PMID 35457026, 2022). "In line with this, the activation of Nrf2 and its targets genes such as HO-1 and NOQ1 ameliorates kidney damage by decreasing the p65 NF-κB subunit along with the priming of NLRP3." (PMID 35204131, 2022). "Unlike these researchers, Tashiro and colleagues did correlate NLRP3 with the severity of kidney damage." (PMID 35457026, 2022). "During the pathogenesis of uric acid-induced nephropathy, uric acid crystals activate the NLRP3 inflammasome, suggesting a novel pathomechanism of crystalline nephropathy." (PMID 35204131, 2022). "This suggests that PSCP protects from HFD-induced kidney damage by blocking the secretion of inflammatory factors and inhibiting the activation of NLRP3 inflammasomes." (PMID 35223948, 2022). "In DN, inhibition of the ROS/NF-κB/NLRP3 pathway appears to reduce inflammation and control the development of progressive kidney damage." (PMID 36401196, 2022). "Collectively, our finding suggests a novel mechanism of NLRP3-mediated RTEC pyroptosis in TCE-induced kidney damage." (PMID 35656289, 2022). "The role of Nrf2/NLRP3 regulation has also been identified in a model of diabetic retinopathy and nephropathy." (PMID 35615474, 2022). "The levels of IL-11 increase.Inhibition of IL-18 can significantly prevent kidney damage.CCL5 and IL-1α slightly increase.Inhibition of TNF-α cannot significantly reduce kidney damage.NLRP3 pathway is the key pathogenesis of inflammation." (PMID 34149721, 2021). "Other studies also had proved that NLRP3 inflammasome plays an important role in the pathogenesis of oxalate-induced nephropathy." (PMID 31183507, 2020). "In summary, we found that the activation of NLRP3 inflammasome participated in the development and progression of AA-induced nephropathy and IL-22 exerted a nephroprotective effect by suppressing renal NLRP3 inflammasome activation." (PMID 31616439, 2019). "This role for TXNIP in the development of diabetic retinopathy and nephropathy has been shown to be involved in NLRP3 inflammasome activation and release of IL-1β." (PMID 30733849, 2019). "Cell-specific knockdown of the NLRP3 inflammasome is required to further address the role of NLRP3 inflammasome activation in tubular epithelial cells in AA-induced nephropathy." (PMID 31616439, 2019). "The production of interleukin-1β resulting from the induction of the NLRP3 pathway in renal mesangial cells through the action of uric acid appears to be another important mechanism for the development of kidney damage." (PMID 31110596, 2019).
kidney damage (continued). "In summary, the present study firstly provides the data that CXCR4/TXNIP is involved in the modulation of the kidney damage via directly regulating NLRP3 inflammasome." (PMID 29849929, 2018). "In many reports, MTD is regarded as important contribution to activation of NLRP3 inflammasome in kidney damage." (PMID 28348462, 2017). "This conclusion is also supported by our human data showing CASP1 mRNA induction only in the tubulointerstitium, where most of the NLRP3 inflammasome-related genes are found to be induced in human nephropathies and where renal dendritic cells reside." (PMID 22046355, 2011). "Supporting evidence indicates that NLRP3 blockade ameliorates HFD-induced kidney damage." (PMID 41586196, 2025). "Moreover, in preclinical models of DN, podocyte-specific activation of the NLRP3 inflammasome is both necessary and sufficient to promote glomerular dysfunction and kidney damage." (PMID 39920111, 2025). "Furthermore, translocated bacterial lipopolysaccharides activate Toll-like receptors and the NLRP3 inflammasome, exacerbating kidney damage and fibrosis." (PMID 40661744, 2025). "The MSU crystal-induced nephropathy was previously shown as the result of stimulation of renal inflammation and fibrosis through activation of the cytosolic Nod-like receptor protein 3 (NLRP3) inflammasome." (PMID 39010902, 2024). "We previously reported the increase of NLRP3 signaling in TCE-induced kidney damage." (PMID 35656289, 2022). "Oral or intravenous infusion of EGCG could reduce mRNA and protein expression of renal NLRP3 in lupus nephritis mouse model and contrast-induced nephropathy rat model, possibly leading to the reduction of NLRP3 inflammasome activation." (PMID 34203004, 2021). "Therefore, in this study, we mainly focused on clarifying that NOX4 activates the NLRP3 inflammasome and leads to pyroptosis, which is related to kidney damage in diabetic mice." (PMID 32456088, 2020). "Furthermore, IL-22 largely inhibited renal activation of NLRP3 inflammasome in AA-induced nephropathy." (PMID 31616439, 2019). "Therefore, in-depth investigations are still needed to clarify the initial priming steps for NLRP3 inflammasome activation in AA-induced nephropathy." (PMID 31616439, 2019). "In addition, in T2DM, the development of nephropathy is associated with the activation of CD8 + T cells and with the increase of interleukin-6 (IL-6), NLRP3 inflammasome, and TNFR1/2 (Tumor necrosis factor receptors 1 and 2)." (PMID 29633887, 2018). "The purpose of this study was to investigate whether Ang II stimulates NLRP3 inflammasome activation through mitochondrial dysfunction during kidney damage." (PMID 27509058, 2016). "Notably, we demonstrated that NLRP3 or Caspase-1 deficiency ameliorated renal tubular injury in a murine model of AAN, thus identifying renal NLRP3 inflammasome activation as a crucial mediator in the pathogenesis of AA-induced nephropathy." (PMID 31616439, 2019). "Nevertheless, it should be pointed out that a more detailed characterization of essential components for NLRP3 inflammasome activation in diverse compartments within renal tissue such as epithelium, endothelium, and interstitium will further benefit the understanding of AA-induced nephropathy." (PMID 31616439, 2019). "Thus, during metabolic endotoxemia, a large amount of lipopolysaccharide from the intestine that goes into the blood may activate the renal NLRP3 inflammasome, resulting in the release of IL-1β and promotion of kidney damage." (PMID 26881256, 2016). "Sodium urate acts as a danger signal in vivo, activating the NLRP3/ASC/Caspase-1 signaling pathway, which plays a pivotal role in inflammation and kidney damage." (PMID 40005069, 2025). "CaOx can induce kidney damage and stone deposition by triggering the formation of GSDMD-N mediated membrane pores and the release of IL-18 and IL-1β via activation of the NLRP3 inflammasome." (PMID 40384863, 2025).
kidney damage (continued). "The NLRP3 signalling is closely related to inflammation, the hyper-activation of NLPR3 inflammasome has been shown to mediate a variety of types of kidney damage." (PMID 34693876, 2021). "Inhibition of NLRP3 inflammasome activation by silencing NLRP3/ASC or repressing caspase-1 activity has been shown to decrease the production of IL-1β and alleviate kidney damage." (PMID 34504642, 2021). "The levels of IL-11 do not increase.Inhibition of IL-18 cannot significantly prevent kidney damage.CCL5 and IL-1α significantly increase.Inhibition of TNF-α can significantly reduce kidney damage.NLRP3 pathway is less important." (PMID 34149721, 2021). "By suppressing NLRP3 inflammasome activation, EGCG-RBCm/NPs may offer a protective mechanism against DQ-induced kidney damage." (PMID 39045044, 2024). "In the current study, we observed that RDV could lower the NLRP3 level, thus inhibiting the NLRP3 inflammasome formation and activation, which facilitated the protective roles of RDV against inflammation-induced kidney damage." (PMID 34093539, 2021). "Besides, ASC-deficient mice were protected from hypertensive nephrosclerosis, and mice lacking NLRP3 were protected from hyperhomocysteinemia-induced glomerulopathy and Western diet-induced nephropathy." (PMID 35204131, 2022). "In addition, we used inhibitors of caspase-1, NLRP3 and GSDMD-N, verifying that inhibition of the pyroptosis process could significantly mitigate proteinuria and kidney damage in PHN rats, indicating the potential for the treatment of MN with inhibitors of Caspase-1, NLRP3, and GSDMD-N." (PMID 35351877, 2022). "The participation of NLRP3 may be less prominent in other modalities of AKI, since NLRP3 KO mice were not protected against kidney damage induced by cisplatin." (PMID 31649546, 2019). "In addition, the mRNA and protein expression levels of NEK7, NLRP3, and ASC in LN patients were significantly lower than those in SLE patients without kidney damage, suggests that this is closely related to the occurrence of LN and could be a protective factor involved in the pathogenesis of LN." (PMID 30202244, 2018).
colon carcinoma (73 papers, 2014 to 2026). "In IBD, the activation of NLRP3 inflammasome-mediated IL-1β release has been shown to be a major risk factor for developing colon cancer." (PMID 39769450, 2024). "In experiments on mouse models with colon cancer, researchers found that NLRP3-deficient mice were highly sensitive to dextran sulfate sodium (DSS) and azoxymethane (AOM)-induced colitis-associated cancer (CAC)." (PMID 38553639, 2024). "Studies have demonstrated that NLRP3 inflammasome polymorphisms are associated with different malignancies such as colon cancer and melanoma." (PMID 37081882, 2023). "For example, NLRP3 was overexpressed in colon cancer cells and linked to the poor survival of patients; NLRP3 inflammasome was activated in gastric cancer, which was beneficial in promoting tumorigenesis." (PMID 37304662, 2023). "By summarizing the somatic mutation frequency of 19 CRGs, we found that ATPA7 and NLRP3 had the highest mutation frequency in colon cancer (5%)." (PMID 37274263, 2023). "Several single-nucleotide polymorphisms in the NLRP3 region associated with hypoproduction of IL-1β and decreased NLRP3 expression are associated with susceptibility to Crohn’s disease, which is a strong risk factor for colon cancer." (PMID 36466820, 2022). "We believe that luteolin causes pyroptosis in HT-29 colon cancer cells by directly activating NLRP3." (PMID 36105214, 2022). "The inhibition of the NLRP3 inflammasome in macrophages from an AOM-dextran sulfate sodium (DSS) mouse model of colon carcinoma significantly protected against colitis-associated cancer." (PMID 30619282, 2018). "Furthermore, the NLRP3 inflammasome has been implicated in the proliferation, migration, and invasion of cancer cells in gastrointestinal cancers, including colon cancer." (PMID 39769450, 2024). "Another study suggested that AKK bacteria could enrich M1-like tumor associated macrophages in the colon cancer microenvironment in NLRP3 dependent way, thereby inhibiting tumor formation and development." (PMID 38650627, 2024). "In addition, the knockdown of NLRP3 in colon carcinoma cells has been associated with a decreased capacity of migration and invasion." (PMID 30619282, 2018). "Based on our previous findings, it was observed that PF exerted promotional effects on the activation of M1 TAMs and attenuated colon tumor pyroptosis by downregulating the NLRP3 signaling pathway." (PMID 41320762, 2025). "Further results demonstrated that SAHA and VPA dose dependently increased NLRP3 levels in four colon cancer cell lines." (PMID 38804602, 2024). "Regarding the mechanism, in vivo, E2 affects important pathways associated with inflammation and colonic tumor development such as NF kB, NRF2 and NLRP3." (PMID 39165688, 2024). "An increased NLRP3 expression was found after ATP-only compared to untreated cells, indicating the self-NLRP3 priming capacity of colon cancer cells." (PMID 38543085, 2024). "Tang and colleagues reported that FL118 inhibited cell proliferation, the migration and invasion of colon cancer cells, and promoted pyroptosis by activating the NLRP3 inflammasome." (PMID 39684769, 2024). "To test the role of NLRP3 inflammasome in colon cancer, we treated mice bearing established colorectal tumors with an inhibitor of NLRP3 (MCC950)." (PMID 38898209, 2024). "Further, small molecular inhibitors such as andrographolide have been shown to protect against azoxymethane and dextran sodium sulfate-induced colon cancer by inhibiting the NLRP3 inflammasome-mediated inflammatory response." (PMID 39769450, 2024). "The NLRP3 inflammasome has also been reported to be highly expressed in mesenchymal-like colon cancer cells." (PMID 37081882, 2023). "GL-V9 is a derivative of baicalein, which degrades NLRP3 inflammasomes by inducing autophagy, and can also delay colon cancer progression and tumorigenesis." (PMID 37020871, 2023).
colon carcinoma (continued). "This NLRP3/caspase-1/GSDMD pyroptosis pathway in response to simvastatin in colon cancer cells was consistent with the previsous study in non-small cell lung cancer." (PMID 37974278, 2023). "Caffeic acid phenethyl ester (CAPE) enhances NLRP3 ubiquitination via facilitating NLRP3–Cullin1 interaction and suppresses NLRP3 inflammasome activation, which protects mice from azoxymethane/dextran sulfate sodium-induced colon cancer." (PMID 37047097, 2023). "NLRP3 was found to be expressed in both immune cells and epithelial cells of colon cancer, manifesting that NLRP3 inflammasomes are involved in the formation of CRC." (PMID 37020871, 2023). "In conclusion, we have revealed that simvastatin induces pyroptosis through ROS/NLRP3/caspase-1/GSDMD pathway in colon cancer." (PMID 37974278, 2023). "A previous study in metastasized colonic tumor indicated that IL18 secretion mediated by NLRP3 was able to induce tumoricidal activities of NK cells against metastatic colon cancer cells in the liver of mouse." (PMID 36276158, 2022). "For instance, Nlrp3-/- mice are more susceptible to chemical-induced colitis-associated colon cancer (CAC), whereas conversely, Nlrp3-/- mice are protected against tumor initiation and progression in a chemical-induced skin carcinogenesis model." (PMID 35299732, 2022). "As a result, the activation of Caspase1 inhibits cancer cell proliferation, and drugs that activate the NLRP3 inflammasome have the potential to be used as a treatment for colon cancer." (PMID 36105214, 2022). "The role of NLRP3 in colon cancer has been controversial with studies showing that high expression of NLRP3 drives epithelial-mesenchymal transition (EMT) and results in poor survival." (PMID 35499706, 2022). "They discovered that the delivery of FADD mediated by TAT in colon cancer HCT116 cells significantly suppressed the canonical NLRP3 inflammasome priming by downregulating NLRP3, thereby restricting the processing and secretion of proinflammatory IL-1β." (PMID 36348274, 2022). "Although there are many types of inflammasomes, NLRP3 inflammasomes are the most extensively studied and most complex caspase-1 inducers in intestinal inflammation and colon tumors." (PMID 34335248, 2021). "In colon cancer cells for instance, LXRβ activates NLRP3 inflammasome by inducing Pannexin1-dependent ATP release and autocrine P2x7R activation, which in turn leads to anti-tumoral effect of LXR agonists." (PMID 33716981, 2021). "Conflicting roles have been described where NLRP3 exhibits a protective role against colon cancer and HCC, while NLRP3 also plays a carcinogenic role in gastric and prostate cancers." (PMID 33613533, 2020). "Inflammasome-independent NLRP3 is required for epithelial-mesenchymal transition in colon cancer cells." (PMID 32508821, 2020). "NLRP3 appears to be important for EMT since inflammasome-independent NLRP3 is enough to EMT in colon cancer cells." (PMID 31766574, 2019). "The NLRP3 inflammasome is a factor for epithelial-mesenchymal transition (EMT) in colon cancer cells." (PMID 31312615, 2019). "Instead, NLRP3 expression in hematopoietic cell compartment is essential for protection against colon cancer." (PMID 28955343, 2017). "For example, NLRP3 exhibits a protective role for colon cancer, but pro-carcinogenic effects for gastric and prostate malignancies." (PMID 27206676, 2016). "The P2X7 activation then leads to NLRP3 inflammasome assembly, and activated caspase-1 that induces colon cancer cell pyroptosis and death." (PMID 27229305, 2016). "Furthermore, the production of IL‐18, which is mediated by the Nlrp3 inflammasome, has the potential to suppress the growth of colon tumors effectively." (PMID 41025546, 2025). "Further, recent studies using various antioxidants have also suggested that oxidative stress-regulated and NLRP3 inflammasome-mediated innate immune and inflammatory response could also contribute to colon cancer growth and spread." (PMID 39769450, 2024).